CRP (C-reactive protein)
Diseases named in the same sentence as CRP in open-access papers (continued):
Sharing a sentence is not in itself a finding about the gene and the disease.
Pleural effusion (continued). "We also found that DM-ILD patients had a higher prevalence of elevated CEA, but a lower prevalence of elevated CA125, lower levels of CRP, CK, and CK-MB, and lower prevalences of pleural effusion and pericardial effusion." (PMID 39364301, 2024). "Infection screen showed high CRP, chest X-ray showed pleural effusion, DFA was positive for entero/rhinovirus, corona NL63, and blood viral PCR was positive for CMV." (PMID 38587703, 2024). "In contrast to the first phase of pleural effusions around day 30, there were also relevant increases in NT-proBNP, CK, CRP as well as several chemokines and pro-inflammatory cytokines, like MCP-1, I-TAC, MIG, IL-6, IL-12, TNF-α and eotaxin." (PMID 39200391, 2024). "The rise in leukocytes, CRP and IL-6 indicates the occurrence of inflammatory processes coinciding with the development of the pleural effusions." (PMID 39200391, 2024). "The prolonged fever, elevated LDH and CRP levels, as well as the presence of pleural effusion and necrotic lung tissue, are consistent with previous studies." (PMID 39949514, 2024). "This definition established PPS when patients qualified for 2 of 5 criteria: fever, pericarditic or pleuritic chest pain, pericardial or pleural friction rub, pericardial effusion, and pleural effusion with elevated C-reactive protein (CRP)." (PMID 38582776, 2024). "In summary, the ADA/CRP ratio has great potential as an additional biomarker for assessing pleural effusions." (PMID 39205740, 2024). "Based on laboratory results, patients with pericardial and pleural effusions exhibited increased levels of C reactive protein, erythrocyte sedimentation rate, NT proBNP, and a higher value of neutrophil/lymphocyte count ratio." (PMID 38999316, 2024). "In human medicine, C-reactive protein (CRP) measured in both serum and pleural effusion, SAA in pleural and peritoneal effusion, and AGP and ceruloplasmin in pleural effusion have all been shown to discriminate between exudates and transudates." (PMID 37370428, 2023). "CRP levels < 0.64 mg/dL are likely to indicate a pleural effusion from congestive heart failure, whereas levels ≥ 1.38 mg/dL are suggestive of an infectious aetiology." (PMID 37730573, 2023). "The diagnosis of PCIS is established if 2 of the following 5 criteria are present: fever without alternative causes, pericarditic or pleuritic chest pain, pericardial or pleural rubs, evidence of pericardial effusion and/or pleural effusion with elevated CRP." (PMID 37394431, 2023). "The results showed that the NLR was a more effective predictor of NP than pleural effusion, CRP levels, preadmission fever duration, LDH levels, and WBC counts, with AUCs of 0.888, 0.834, 0.827, 0.784, 0.729, and 0.725, respectively." (PMID 38169689, 2023). "Regarding variables that had a linear correlation with the AI-CXR score, CRP, albumin, and lymphocyte percentage showed a close correlation across all time categories with both consolidation and pleural effusion scores." (PMID 37762792, 2023). "Their research identified respiratory rate, dyspnea, lung moist rales, LDH, BUN, CRP/ALB ratio, and pleural effusion as potential predictors for ICU admission risk." (PMID 37685276, 2023). "Patients with poor outcomes had a significantly higher age (p = 0.009), higher blood glucose (p < 0.001), higher CRP (p = 0.002), lower oxygen saturation (p = 0.018), and more cases with pleural effusion (p = 0.001)." (PMID 37305146, 2023). "The tool for predicting ICU admission composed of the following factors: respiratory rate, dyspnea, lung moist rales, LDH, BUN, C-reactive protein/albumin ratio, and pleural effusion." (PMID 36424963, 2022). "During both admissions, he was diagnosed with acute pericarditis, and his workup was significant for elevations in D-dimer and CRP as well as pericardial and pleural effusions." (PMID 35784959, 2022).
Pleural effusion (continued). "The same 16 variables (SIRS, hematocrit, platelets, prothrombin time, albumin, AST, glucose, serum creatinine, BUN, cholesterol, HDL, LDL, triglyceride, serum calcium, C-reactive protein, and pleural effusion) were used for the RF model." (PMID 35755843, 2022). "Various other studies have highlighted the relationship between pleural fluid CRP and the etiology of pleural effusion with similar findings." (PMID 35874904, 2022). "Even without a history of aspiration, risk factors, and typical imaging findings, patients with acute chest pain, fever, exudative pleural effusion, elevated leukocytes, CRP, and ESR levels should have a low threshold for aspiration pneumonia diagnosis." (PMID 36605125, 2022). "Multiple studies have been conducted regarding the role of pleural fluid CRP in diagnosing exudative pleural effusion worldwide." (PMID 35874904, 2022). "Older age, longer duration of fever during the illness, higher CRP and LDH levels, and lower lymphocyte (%) levels were associated with the development of pleural effusion in MP pneumonia." (PMID 34578108, 2021). "Prevalence of pleural effusion in different level of C-reactive protein and scoring systems in 465 patients with acute pancreatitis." (PMID 34727802, 2021). "We noticed that patients with pleural effusion, low CRP (mean = 1.7), and low ADA (mean = 18.1) tend to be classified as MPE." (PMID 34575641, 2021). "The relationship between pleural effusion volume and C-reactive protein level, and different scoring systems in 465 patients with acute pancreatitis." (PMID 34727802, 2021). "Patients with pleural effusion, low CRP (mean = 2.3), and moderate-high ADA values (mean = 74.3) tend to be classified as TPE." (PMID 34575641, 2021). "Pairwise comparison of AUC of pleural effusion volume, C-reactive protein and different scoring systems in 465 patients with acute pancreatitis." (PMID 34727802, 2021). "Receiver operating characteristic curve analysis of pleural effusion volume, C-reactive protein and different scoring systems for predicating severity and clinical outcomes of acute pancreatitis in 465 patients." (PMID 34727802, 2021). "Patients with pleural effusion, mean-high CRP values (mean = 10.9), and moderate-high ADA values (mean = 49.3) tend to be classified in the PPE category." (PMID 34575641, 2021). "We observe, therefore, that patients receiving a diagnosis of PPE have significantly higher p-CRP levels than patients with another diagnosis of pleural effusion." (PMID 34575641, 2021). "The prevalence of pleural effusion in different level of CRP and scoring systems of the 465 AP patients were also observed with significant differences present between the different subgroups (all the p-values were <.0001)." (PMID 34727802, 2021). "Based on the results of this retrospective cohort study, pleural effusion, baseline CRP levels > 1.0 mg/dL, and use of steroids prior to treatment tended to reduce the effectiveness of first-line monotherapy with pembrolizumab." (PMID 32013910, 2020). "For the clinical features, fever, pleural effusion, high white blood cell count and CRP, and low level of serum albumin were more frequently seen in patients with advanced CKD than in those with early CKD." (PMID 32349734, 2020). "Autoimmune profile was normal, inflammatory markers including erythrocyte sedimentation rate (ESR) and C-reactive protein (CRP) were raised, and an ultrasound and a plain radiograph of the chest confirmed the right-sided pleural effusion." (PMID 30967975, 2019). "Univariate analysis identified death related biomarkers, mainly including MIF levels, age, cavitary lesion, pleural effusion, drug-resistant, disseminated status and CRP, IL-6 and ALB." (PMID 30841876, 2019). "The aim of the present study was to evaluate the pleural fluid concentrations of presepsin, CRP, and PCT in patients with pleural effusions of various causes and to explore the usefulness of these markers in predicting an infectious aetiology." (PMID 30470216, 2018).
Pleural effusion (continued). "Nevertheless, the plasma fibrinogen concentration in dogs with pleural effusion was similar to sick control dogs, despite a significantly increased serum CRP concentration in comparison to these dogs." (PMID 29462172, 2018). "CRP levels < 0.64 mg/dL are likely to indicate a pleural effusion from congestive heart failure, whereas levels ≥ 1.38 mg/dL are suggestive of an infectious etiology." (PMID 27194820, 2016). "Pleural CRP has recently been proposed as a specific biomarker for the differential diagnosis of pleural effusions and reportedly exhibits higher sensitivity and specificity than serum CRP." (PMID 27194820, 2016). "Single indicators such as blood glucose, pleural effusion, and C-reactive protein (CRP) are also used to predict the severity of diseases, which greatly simplified the evaluation process; However, these indicators have poor sensitivity and specificity." (PMID 26580397, 2015). "Univariate regression analysis showed that atelectasis, pleural effusion, high PCT level, high fibrinogen level, high D-dimer level, and high CRP level were significantly associated with the occurrence of long-term adverse prognosis (BO or bronchiectasis diagnosed within one year after discharge)." (PMID 40654577, 2025). "We evaluated the association of affordable lab works, such as C-reactive protein (CRP), procalcitonin, ferritin, neutrophil and lymphocyte counts, D-dimers, and albumin levels, with the extents of lung injury, pleural effusion, pulmonary embolism, and thoracic adenopathy." (PMID 40428888, 2025). "SHAP (SHapley Additive exPlanations) value analysis, which quantifies the contribution of each input feature to the model’s predictions, showed that the top five variables (CRP, age, spleen size, pleural effusion volume estimate, symptom fever) were identical across both scenarios." (PMID 40901833, 2025). "However, heterogeneity for LDH, WBC, IL-6, AST, ALT, Neutrophils (%), CRP, and Combined pleural effusion remained largely unchanged." (PMID 40656195, 2025). "Interestingly, despite having a lobar pneumonia with pleural effusion and respiratory distress, the patient showed a poor inflammatory response, with low fever and maximal C-reactive protein (CRP) of 39 mg/L (normal range < 10 mg/L)." (PMID 40977713, 2025). "CRP 165 mg/L, ESR 51 mm/hour; CT of chest and abdomen showed a 2.5 cm defect in the left hemidiaphragm with herniation of the gastric fundus and associated pleural effusion." (PMID 41409928, 2025). "Additionally, bilateral pleural effusion was noted, and the pneumonia had progressed compared with the previous state (and IL-6: 3557 pg./mL, CRP: 316 mg/L)." (PMID 41169424, 2025). "Mean ± standard deviation for serum CRP values for pleural effusions." (PMID 39205740, 2024). "Chest X-ray revealed pleurisy with pleural effusion, an increased level of C-reactive protein (CRP) (161 mg/L, normal: 0–5 mg/L), and an erythrocyte sedimentation rate of 40 mm/h (normal: 0–10 mm/h); blood tests showed the presence of lupus anticoagulant and ANA." (PMID 39201720, 2024). "Mean ± SD and p-value for ADA/CRP ratio for pleural effusions." (PMID 39205740, 2024). "However, pericardial effusion and pleural effusion, elevated creatinine kinase, and elevated C-reactive protein were more common in ASS-ILD patients." (PMID 39364301, 2024). "Patients with lung lesions involving two or more lobes, a large amount of pleural effusion, high levels of inflammatory markers (CRP level of ≥ 25.92 mg/L, LDH level of ≥ 378 U/L), or a long hospital stay (a hospitalization time of ≥ 10.5 days) had longer radiographic resolution." (PMID 38641804, 2024). "The variables used were respiratory distress, oxygen saturation ≤ 90% or cyanosis, oxygen support during hospitalization, oxygen support (days), AST, ALT, CRP, lobar pneumonia at admission, atelectasis at admission, pleural effusion at admission and any extrapulmonary manifestations." (PMID 35054002, 2022).
Pleural effusion (continued). "We found that smoking history, pleural effusion, number of treatment lines, acute phase proteins (IL-6 and CRP), CD8 + T lymphocyte count and serum alveolar epithelial proteins (including SP-A, SP-D and KL-6) were different between the CIP and non-CIP groups in the training cohort (P < 0.1)." (PMID 36050683, 2022). "Interestingly, not only cardiac biomarkers such as serum NT-pro BNP and troponin T, but also GGT and CRP levels were higher in patients with pleural effusions." (PMID 32914241, 2021). "ECOG PS score ≥ 2, stage IV disease or recurrence, a TPS of 50–90%, use of steroids prior to treatment, the presence of pleural effusion, and baseline CRP levels > 1.0 mg/dL yielded a p < 0.10 in the univariate analysis, and were included in the multivariate analysis." (PMID 32013910, 2020). "Compared with early CKD, advanced CKD was associated with significantly higher rates of disseminated cryptococcosis and nonrecovery after treatment and more frequent clinical features of fever, pleural effusion, high white blood cell count and CRP, and low level of serum albumin." (PMID 32349734, 2020). "In the univariate analysis, a PS of 2‐4, never smoking, driver mutations including those of EGFR and ALK, LDH ≥ 240 IU/L, CRP ≥ 1 mg/dL, NLR ≥ 4, liver metastasis, brain metastasis, pleural effusion, and steroid use at the commencement of nivolumab treatment were associated with a shorter PFS." (PMID 31880861, 2020). "In this study, children with RMPP had longer hospital stays and duration of fever, more frequent occurrences of pleural effusion, mucus plug, and expulmonary complications, as well as significantly higher levels of CRP and LDH in peripheral blood, compared with NRMPP cases." (PMID 31399022, 2019). "Pleural effusions, venous thrombosis, and CRP elevation were identified as novel potential risk factors for adverse outcomes." (PMID 30652419, 2019). "We hypothesised that pleural fluid presepsin, CRP, and/or PCT concentration(s) may be of value in the differentiation between several causes of pleural effusions." (PMID 30470216, 2018). "We have demonstrated that PCT when measured in all patients presenting with unilateral pleural effusion to a tertiary pleural service offers no greater diagnostic utility than WCC or CRP." (PMID 28158976, 2017). "Moreover, elevated CRP values in pleural effusion had high sensitivity and specificity for the differential diagnosis of para-pneumonic effusion and other exudative effusions." (PMID 27759851, 2016). "Multivariate analysis demonstrated that elevated CRP level at the second week post-PLA diagnosis (p = 0.001), location near the right diaphragm (segments 7 and 8, p = 0.048), and larger liver abscess diameter (p = 0.042) were statistically significant risk factors of pleural effusion." (PMID 31842761, 2019). "Furthermore, when distinguishing between parapneumonic pleural effusion and other types of effusions (excluding empyema in both groups), pleural fluid presepsin levels of > 680 pg/mL and pleural fluid CRP levels of > 2.18 mg/dL yielded the highest accuracy rate (90.1%)." (PMID 30470216, 2018). "This study identified CRP, PLT, Prior biliary disease, Fever, Pleural effusion, Ascites, Broth culture, DM, and TBIL as significant predictors of the occurrence of IKPLAS in liver abscess patients." (PMID 41393139, 2025). "These indicators included inflammatory factors and other features such as CRP, LDH, ESR, WBC, IL-6, neutrophil count (%), AST, ALT, duration of fever, lung consolidation, and pleural effusion." (PMID 40656195, 2025). "based on CRP and LDH, integrated lung ultrasound-related indicators such as pleural effusion and consolidation size/body surface area (BSA), resulting in an AUC of 0.955 (95%CI: 0.919–0.978) for predicting RMPP." (PMID 40171163, 2025).
Pleural effusion (continued). "The variables significantly impacting the model’s predictions included CRP, neutrophil count, NAR, BMI, calcium ion levels, lactate, age, CT grade, Lym, blood amylase, and pleural effusion." (PMID 40873797, 2025). "A C-reactive protein (CRP) at that time was 38.5 mg/dL (reference range 0–1.0 mg/dL), and a repeat chest X-ray demonstrated a new right pleural effusion." (PMID 40918072, 2025). "Age, AGR, NLR, CRP, ESR, MPV, coinfection, pleural effusion, primary disease, fever days ≥ 7 and wheeze were independent risk factors for SMPP in children." (PMID 38589453, 2024). "After adjusting for potential confounding variables (age, sex, body mass index, comorbidity, albumin, ejection fraction, c-reactive protein, RRF, and Total Kt/Vure), the overall mortality in pleural effusion raised significantly with HR 3.06 (2.36–3.96)." (PMID 38241413, 2024). "In the training cohort, the levels of WBC, N%, NLR, CRP, ESR and MPV in the SMPP group were higher than those in the GMPP group, as were incidence of primary disease, coinfection, pleural effusion, fever days ≥ 7 and wheeze." (PMID 38589453, 2024). "The comparison between the mild and severe groups showed statistically significant differences in age, fever, wheezing, CRP, white blood cell count, MLUS score, pleural effusion, and pathogens (P < 0.05), suggesting the potential factors influencing severity." (PMID 39161635, 2024). "According to the results of the multivariate logistic regression, we constructed a nomogram model including age, AGR, NLR, CRP, ESR, MPV, coinfection, pleural effusion, primary disease, fever days ≥ 7 and wheeze." (PMID 38589453, 2024). "Age, AGR, NLR, CRP, ESR, MPV, coinfection, pleural effusion, primary disease, fever days ≥ 7 and wheeze are independent risk factors for SMPP in children." (PMID 38589453, 2024). "The results showed that age, AGR, NLR, CRP, ESR, MPV, coinfection, pleural effusion, primary disease, fever days ≥ 7 and wheeze were independent risk factors for SMPP (P < 0.05)." (PMID 38589453, 2024). "Based on age, AGR, NLR, CRP, ESR, MPV, coinfection, pleural effusion, primary disease, fever days ≥ 7 and wheeze, the first dynamic nomogram for accurately predicting SMPP was successfully established." (PMID 38589453, 2024). "In pleural effusion, NLR (AUC: 0.83, p = 0.02), ADA (AUC: 0.8, p = 0.02), and C-reactive protein in blood (AUC: 0.87, p = 0.003) demonstrated robust diagnostic capabilities." (PMID 38742106, 2024). "The IL‐8, IL‐1β, sIL‐2R, WBC, CRP, PCT, SAA, ESR, ALT, ferritin, FIB and pleural effusion were excluded from the analysis due to their high non‐response rate." (PMID 37142438, 2023). "ROC analysis showed that the NLR predicted the incidence of NP with greater accuracy than pleural effusion, preadmission fever duration, WBC counts, and CRP and LDH levels." (PMID 38169689, 2023). "white blood cell (WBC) count, C-reactive protein (CRP), bilateral change, pleural effusion on chest imaging, and pathogen detection showed significant differences among patients presented with NSCAP and SCAP." (PMID 38259459, 2023). "More ICU inpatients had dyspnea, lung moist rales, and pleural effusion; significantly higher respiratory rate, heart rate, LDH, BUN, CRP, and CAR; and significantly lower lymphocyte, albumin, and CD8+ T lymphocyte counts (all P < 0.05)." (PMID 36424963, 2022). "The recurrent fever, leukocytosis and/or elevated C-reactive protein (CRP), and a considerable amount of residual pleural effusion, revealed by radiological examinations, always indicate the failure of fibrinolysis therapy." (PMID 36605125, 2022). "These established biochemical markers (CRP and ADA) aid in the differential diagnosis of various etiologies’ pleural effusions." (PMID 34179342, 2021).